SNORA18 (small nucleolar RNA, H/ACA box 18)
Synonyms: ACA18
Gene: Small nucleolar RNA gene on chromosome 11 (93,733,466 to 93,733,597, reverse strand). Ensembl gene ENSG00000207145.
Gene Ontology:
Biological process: RNA processing
Cellular component: nucleolus
Homologues: Orthologues: chimpanzee SNORA18 (99% identical), macaque SNORA18 (98% identical), mouse Gm24455 (86% identical), rat LOC120101255 (86% identical), rat Snora18 (86% identical).
Diseases named in the same sentence as SNORA18 in open-access papers:
SNORA18 is named in the same sentence as 3 diseases in open-access papers, as found by Europe PMC text mining. Sharing a sentence is not in itself a finding about the gene and the disease. The quoted sentences say what the papers report.
pancreatic cancer (2 papers, 2022 to 2025). "Additionally, through its interactions with the small nucleolar RNAs SNORA18 and SNORA22, KSRP has been demonstrated to promote the invasiveness and metastasis of pancreatic cancer cells." (PMID 40699755, 2025).
tumor (2 papers, 2020 to 2022). "Consequently, SNORA18 and SNORA22 contributed to cell invasiveness and tumor metastasis." (PMID 32010427, 2020).
SNORA18 also shares sentences with these, for which no sentence is quoted: hepatocellular carcinoma (1 paper).